IL1B (interleukin 1 beta)
Diseases named in the same sentence as IL1B in open-access papers (continued):
Sharing a sentence is not in itself a finding about the gene and the disease.
tumor (continued). "As tumour-derived IL-1B compensated for the absence of microenvironment-derived IL-1B, we next hypothesised that IL-1B production by tumour cells restores the infiltration of innate immune cells that may harbour anti-tumour functions, resulting in a reduction in primary tumour growth." (PMID 34290237, 2021). "Besides, IL1B and CD80 were detected to be significantly increased in the HEY cells with APOBEC3A upregulation, indicating that APOBEC3A could accelerate the transformation of M0 macrophages to M1 in tumor immune microenvironment of OC patients." (PMID 34745121, 2021). "Importantly, some of the cytokines and chemokines upregulated in the tumor were also elevated in the plasma of mice receiving heterologous KV vaccine, including increased levels of IFN-γ, CCL5, CXCL10, CCL2, IL-6, CXCL1, and IL-1β one day after VSV-GP-HPV boost." (PMID 34465781, 2021). "Thus, IL-1β may not promote tumor development through sustained long-term inflammatory stimulation, but may inhibit tumors through an anti-tumor immunity." (PMID 32556504, 2020). "However, depending on the cancer type or stage, the main type of immune cells present in the tumor microenvironment, and the anti-cancer treatment used, inhibiting IL-1β may or may not be beneficial for patients." (PMID 32635472, 2020). "Additionally, tumor cells are capable of producing mediators of chronic inflammation, such as granulocyte-macrophage colony-stimulating factor (GM-CSF), vascular endothelial growth factor (VEGF), TNF-α, IL-1β, and IL-6, which induce the generation and expansion of MDSCs in situ." (PMID 33042814, 2020). "Notably, RNAs isolated from parental tumor cells could not induce IL-1β expression, suggesting that unique RNA(s) in L-MPs is responsible for the TLR3 activation." (PMID 31649305, 2020). "However, it seems that some of the well-defined proinflammatory cytokines such as TNFα, IL-1β, and IL-6 may not play the role as the expression of these cytokines were remarkably downregulated in tumor tissues." (PMID 32382012, 2020). "Affymetrix array and real-time PCR analysis reviled significantly increased IL-1B in human bone discs implanted into mice 4-weeks after intra-mammary injection of tumour cells into the mammary ducts compared to human bone discs isolated from mice that did not receive injections of tumour cells." (PMID 31783893, 2019). "Moreover, researchers have found that in animal and human breast cancer models, the inflammasome and IL-1β pathway promotes tumor proliferation and migration and that mice lacking inflammasome components exhibit notably suppressed tumor growth and lung metastasis." (PMID 31242947, 2019). "Interestingly, this in vivo NF-κB response of KRASMUT cells was abolished in IL-1β-deficient (Il1b−/−31), but not in TNF-deficient (Tnf−/−32), mice, indicating that KRASMUT tumor cells selectively respond to IL-1β of the pleural environment by activating NF-κB." (PMID 29445180, 2018). "The poor clinical outcome associated with the BRD4+/high group in the absence of T-bet+ TILs suggests that BRD4 may promote tumor progression through upregulation of chronic inflammatory pathways marked by the production of proinflammatory cytokines such as IL-1α, IL-1β, and IL-6." (PMID 30029633, 2018). "In order to clarify the mechanism by which hAAT may act to affect tumor-infiltrating macrophages in such a context-dependent manner, BMDMs were pretreated with hAAT and then cocultured with RMA tumor cells, with or without stimulation with recombinant IFNγ and IL-1β." (PMID 28003813, 2016). "Besides their function against several types of tumor, CD45RB+ T cells seem to be involved with the inflammasome-IL-1β production that might contribute to the lower levels of this cytokine in the lesions and lymph nodes in the KO mice as compared with WT group." (PMID 25268644, 2014).
tumor (continued). "Our data demonstrates that while the level of GM-CSF, IL-1α and IL-1β per mg of tumor does not change following radiation therapy, the decrease in size of the tumor will result in fewer of these and other tumor-derived growth factors in the tumor-bearing mouse following radiation therapy." (PMID 23936036, 2013). "However, the immunogenicity seen with the inhibition of Msr1 on tumor derived DCs is not through the induction of IL-1β, as we show that irradiated tumor derived DCs produce significantly more IL-1β than non-irradiated tumor derived DCs incubated with either no, 10,25 or 50 ug/ml of Msr1." (PMID 22911764, 2012). "Given that radiation can induce macrophages to release IL-1β in the absence of tumor cells in vitro, it is intriguing to consider whether, in vivo, this effect may contribute to the development of anti-tumor immunity after radiotherapy." (PMID 23112958, 2012). "Since we demonstrated that IL-1β-induced collagen invasion of RCC cells was dependent on MMP enzymatic activity and that IL-1β-induced MMP expression was dependent on CEBPβ, we next asked whether or not CEBPβ was required for IL-1β-mediated RCC tumor cell invasion." (PMID 23342250, 2012). "Indeed, macrophages and IL-1β failed to inhibit TRAIL induced apoptosis in Snail deficient HCT116 or Hke-3 cells, confirming that macrophages and IL-1β protect from TRAIL-induced apoptosis through stabilization of Snail in tumor cells." (PMID 20661477, 2010). "Tumor CyTOF and histology showed T-cell and microglial enrichment in SB28 but not GL261 after Apoa1 or Il1b gene therapy treatments." (PMID 40161763, 2025). "Without IL-1β, there was increased IL-12 production and activation of CD8+ T cells that attacked the tumor." (PMID 41007766, 2025). "Given anti-IL-1β treatment resulted in an increase in all CAF subpopulations in the KPC-3403 tumor, no obvious DGE was observed in the control versus anti-IL-1β treated samples as anticipated." (PMID 39948655, 2025). "In the NT GSDMD-treated group we achieved prolonged survival compared to the empty vector-treated mice, yet tumor growth did not cease, whereas NT GSDMD + IL-1β therapy resulted in tumor suppression and survival of 17% of treated mice." (PMID 39737979, 2024). "Meanwhile, the mRNA and protein expression levels of NLRP3, caspase 1, GSDMD, IL-1β and IL-18 in H(FMT) group were higher than that in T(FMT) group, while there were no noticeable difference between T(FMT) group and tumor model group." (PMID 40046008, 2024). "In contrast, a non-significant difference was observed in IL-1β expression in both AC and SCC tissues compared to para-tumor tissues (all p > 0.01)." (PMID 38103126, 2024). "Exceptions to this pattern were IL1B, which was transcribed predominantly by myeloid cells irrespective of the CALB1 status of the tumor, and CCL26, which was transcribed predominantly by CALB1-expressing cancer cells." (PMID 37192000, 2023). "Macrophage-derived IL-1β induces non-neuronal cells to synthesize NGF, and tumor cells can also secrete NGF and BDNF to active their Trk receptors to stimulate nerve growth." (PMID 36900158, 2023). "One often reported cytokine subfamily upstream of TNFα is IL-1α and IL-1β; of which, IL-1α, but not IL-1β, is produced during MMTV-PyMT tumor pathology." (PMID 37134077, 2023). "Multiple proinflammatory/immune recruitment (IL-1β, IL-6, IL-8, TNFα, IFNα, MIP-1β, CXCL12) and immune suppressive cytokines (IL-10) were found to be induced by tumor line-derived sEVs but not those derived from normal pancreatic cell lines." (PMID 37834100, 2023). "The absence of mature IL-1β in malignant cells strongly suggests that NLRP7 functions in an inflammasome-independent pathway, which contributes to the exacerbation of tumor-dependent cell proliferation and invasion." (PMID 35203462, 2022).
tumor (continued). "Further analysis showed that the contents of IL-10 and TGF-β was significantly increased in tumor tissues, but there were no significant changes of TNF-α, IL-6, and IL-1β observed compared with the control group." (PMID 35646112, 2022). "In the tumor microenvironment, MDSCs significantly contributed to the increase of VEGF-A, but not of IL-1β, under HFHCD and exerted increased immunosuppressive activities." (PMID 36104342, 2022). "Intriguingly, these observations were almost further validated by our real‐time qPCR results of five pairs of tumor and adjacent nontumor samples, such as COL1A1, MMP1, MMP10, CXCL8, and IL1B." (PMID 34821009, 2022). "EBVaGC also has an upregulation of IL-1β and IFN-γ, and lower tumour regulatory genes when compared to EBV negative GC." (PMID 34956172, 2021). "Although dose‐related increase of several proinflammatory cytokines (such as IL‐1β, TNF‐α, IL‐6, and IL‐12) was observed, no patients experienced objective tumor regression." (PMID 33854892, 2021). "Our results indicated that cleaved IL-1β and IL-18 were extremely low, regardless of the expression level of AIM2 in tumor cells." (PMID 33391539, 2021). "We found that the growth of IL-1B overexpressing primary tumours was increased in IL1R1−/− mice compared to IL1R1fl/fl mice, suggesting that tumour-derived IL-1B can no longer exert its anti-tumour functions in IL1R1-deficient microenvironments." (PMID 34290237, 2021). "RNA-seq data also demonstrated that several genes related to adoptive immune systems which have pro-tumor action, such as TGFβ2, TGFBI, TGFBR1, TGFBR3, PLAU, IL-1β, and IL-33 are higher in Pn-positive cells than Pn-negative cells." (PMID 34680221, 2021). "None of the JAKi studied were able to completely block IL-1β production by GM-CSF-stimulated THP-1 cells, a human monocyte-lineage tumor cell line." (PMID 32539713, 2020). "The indiscrimination in the baseline levels or changes following pleurodesis of IL-1-β, IL-6, and TGF-β between patients with or without successful pleurodesis was consistent with their reported dual tumor promoting or inhibitory function." (PMID 33322487, 2020). "NHE-06 administration decreased IL-6 levels and downregulated IL-1β and COX-2 expression in mice bearing subcutaneous Hepa1-6 tumors, which is indicative of inactivated NF-κB/IL-6/STAT3 signaling and restored tumor immunity without direct tumor cytotoxicity." (PMID 32595757, 2020). "What's more, Xue and colleagues reported that IL-1β combined with IL-4, in the absence of TGF-β, induced a non-canonical Th9 subset that was less exhausted and showed superior anti-tumor effects to classic Th9 cells induced by TGF-β and IL-4." (PMID 32508847, 2020). "Conversely, the pharmacological blockade of P2X7R in wtAT mice, besides reducing tumor growth, promoted an anti-tumor immune infiltrated with incremented IFN-γ and reduced IL-1β, but without affecting the TME exATP." (PMID 32635260, 2020). "In line with this notion, blockade of the ActRIIB receptor to inhibit Mstn signaling prevented cachexia in C26 tumor bearing mice, without affecting increased circulating levels of IL-6, TNF-α, and IL-1β." (PMID 33329046, 2020). "Here, we determine that non-canonical IKKα-RelB pathway activation of KRAS-mutant tumor cells mediates MPE development and this is fueled by host-provided interleukin IL-1β." (PMID 29445180, 2018). "Consistent with the in vitro data, IL-1β-producing cells were CD45.2−, indicating that EG7 tumour cells and OT1 CTLs do not produce IL-1β." (PMID 28537251, 2017). "Our finding on the increase of serum TNFα and IL-6, but not IL-1β, in LLC tumor-bearing mice is similar to these patient data." (PMID 28536426, 2017). "This indicates that caspase-1 or its final product, IL-1β, is not crucial for HNSCC cell survival in isolated conditions without a surrounding tumor microenvironment." (PMID 28430665, 2017).
tumor (continued). "Interestingly, we also found that the treatment of IL1β could not fully rescue the defect in tumour sphere formation upon NEDD4 knockdown, despite that IL1β alone readily increased the tumour sphere numbers in control cells, indicating that there are other important factors involved." (PMID 28300060, 2017). "We found that OT1 CTLs quickly induced IL-1β secretion and IFN-γ production in the EG7 tumours but not in EL4 tumours." (PMID 28537251, 2017). "IL-1β and TNF-α levels in the cortex and hippocampus did not vary with tumor status or treatment (data not shown)." (PMID 27893434, 2017). "Il1β−/− mice, however, failed to gain weight with HFD and had reduced tumour growth in ND- and HFD-treated mice, compared with the WT counterparts." (PMID 27708283, 2016). "Moreover, IL-1β was found to induce cyclooxygenase (COX)-2 expression that together with PGE2 could not only mediate an accumulation of MDSCs and TAMs and stimulate tumor progression but also prevent the maturation and activation of antigen presenting cells at the tumor site." (PMID 27827871, 2016). "Although TAMs contribute significantly to production of VEGF, IL-1β, TNF-α, IL-6, IL-23, IL-8, MMPs which have pro-angiogenic and growth attributes, specific molecular pathways in macrophages that immunoedit tumor growth are not well defined." (PMID 24842612, 2014). "We found minimal detection of pro-inflammatory cytokines in the serum of the NT group (normal mice without tumor), whereas, tumor bearing mice had significantly elevated levels of TNF-α, IL-6 and IL-1β." (PMID 24885825, 2014). "Levels of proinflammatory cytokines IL-1β, IL-18, Tumor Necrosis Factor (TNF)-α and Interferon (IFN)-γ were decreased in the tumor microenvironment in the absence of inflammasome proteins." (PMID 25268644, 2014). "While no statistical differences in IL-1β, CCL-7, CCL-8, CCL-24 and CXCL-5 gene expression were confirmed among four tumor groups." (PMID 24260500, 2013). "Our in vivo results identifying FABP4, IL-1β and HMOX-1 as factors influencing invasiveness and tumor growth in the bone but not in the subcutaneous site were recapitulated using bone marrow adipocyte cultures in vitro." (PMID 24240026, 2013). "Largely infiltrating neutrophils were observed in B16F10-IL-1β tumours, but not in B16F10-pro-IL-1β and B16F10-vector tumours." (PMID 23065753, 2012). "In agreement with the expression pattern of the other pro-inflammatory NFκB target genes TNFα and IL-1β, we found that COX-2 levels were dramatically decreased with PDTC treatment in non-tumor bearing skin but not in tumors." (PMID 22761871, 2012). "As vitamin D3 acts as an inhibitor of IL1-β release, its activity was prevented by exogenous IL1β and was dependent on the expression of VDR on macrophages and not on tumor cells (data not shown)." (PMID 20661477, 2010). "Inserts were placed on culture wells containing confluent human dermal fibroblast (negative control), tumour cell lines, and HMVEC previously treated with 10 U/mL of human recombinant IL-1β for 5 hours (positive control)." (PMID 20169105, 2009). "IL-2 and IL-13 were not correlated with PR status, whereas IL-1β, IL-6, IL-8, IL-10, IFN-γ, MCP-1, MIP-1β, TNF-α and, to a lesser extent, IL-4, IL-12 and G-CSF were more abundant in PR-negative tumours than in PR-positive ones." (PMID 17261184, 2007). "This conflicts with the findings of Zheng and Liu, who discovered higher expression of NLRP3, ASC, caspase‐1, and IL‐1B in lymph node‐positive PDAC cases; however, it is worth noting that their study included only stage I–II tumors and segmentation of tumor cells from stroma was not performed." (PMID 39969214, 2025). "However, anti-IL-1β treatment appears to enhance CAF and immune cell infiltration without altering their functions in the KPC tumor with lung metastasis tropism." (PMID 39948655, 2025).
tumor (continued). "Similarly, anti-IL-1β treatment increased the infiltration of CD8 + and CD4 + T cells in the KPC-3403 tumor compared to the control sample; and no significant DEGs were identified in the control versus anti-IL-1β treated samples." (PMID 39948655, 2025). "In patients treated with both nivolumab and ipilimumab, IL-1β and sTNFR-1 were not significant prognostic factors for PFS or OS, suggesting that ipilimumab may be involved in tumor immunity by regulating the activity of IL-1β and sTNFR-1." (PMID 38580797, 2024). "Furthermore, CAR-M and CAR-shSIRPα-M exhibited increased secretion of IL-1β, IFN-γ, and TNF-α, regardless of tumor antigen stimulation." (PMID 39379603, 2024). "Interestingly, in tumors lacking the Il1b gene, there was a significant induction of chemokine CCL7, in contrast to the in vitro data performed with tumor cell cultures." (PMID 37733448, 2023). "Macrophage-derived IL-1β induces non-neuronal cells to synthesize nerve growth factor (NGF), and activated macrophages can also release glial cell-derived neurotrophic factor (GDNF)-activated RET receptors to trigger tumor cell migration." (PMID 36900158, 2023). "Notebly, only live ID8 cells could enhance IL-1β secretion but not transcription by BMDMs after LPS stimulation, suggesting a direct cell-cell interaction pathway between ID8 tumor cells and BMDMs that boosts IL-1β secretion." (PMID 37932814, 2023). "Based on these observations, we hypothesized supplementing stroma-derived factors, such as IL-1β, could restore PDGFB-driven (PN), but not Nf1-silenced (MES), tumor cell production of MCPs." (PMID 37733448, 2023). "Although WGP upregulated IL-1β in M1, WGP could not enhance tumoricidal activity, implying non-cytokine-dependent anti-tumor mechanisms." (PMID 36142859, 2022). "In addition, significant negative correlations were detected between IL-1β secretion and tumour dimensions, LUH and LUD, and IL-8 and tumour dimensions in 1,4-dihydroxy quininib treated samples." (PMID 36698840, 2022). "As TNFα and IL-1β inhibitors are now available to treat severe ICB induced immune related adverse events, it is encouraging that blocking these pathways did not diminish the anti-tumor responses of chemo-immunotherapy in preclinical models." (PMID 35634282, 2022). "IDO‐1, KYNU, PAPP‐A, and IL‐1B were not upregulated in CEF‐CM‐treated CAFs, suggesting that CEFs do not amplify pre‐existing CAF function, but that newly differentiated CEFs can promote tumor progression." (PMID 34379869, 2022). "Moreover, the expression of caspase-1, IL-1β, and GSDMD was negative correlation with increasing tumor grade, clinical stage, and poor clinical prognosis in BC, indicating pyroptosis played a central role in BC tumorigenesis and progression." (PMID 35464869, 2022). "While DOX administration in tumor-free mice did not result in significant changes in the expression of inflammatory markers in the heart, DOX administration significantly abrogated the tumor-induced upregulation of IL-1β, Mcp-1, Cxcl9, and Cxcl10." (PMID 34445729, 2021). "However, CAPE did not affect NLRP3 or IL-1β transcription, but instead enhanced NLRP3 binding to ubiquitin molecules, promoting NLRP3 ubiquitination, and contributing to the anti-tumor effect in the AOM/DSS mouse model." (PMID 32435622, 2020). "Therefore, similar to IL-1β, PTGS2 will not promote tumor progression through sustained inflammatory stimuli in early-stage LUAD." (PMID 32556504, 2020). "A possible explanation for the lack of increased NLRP3 expression, despite elevated caspase-1, IL1β and IL18, is that only specific locations have cells with activated NLRP3 (i.e., a cluster of invading immune cells at the tumor/tissue interface) and tissue was from regions without altered NLRP3." (PMID 31923221, 2020). "To study whether increased inflammasome activation could be responsible for tumor control in mice lacking Tmem176b, we blocked IL-1β and studied EG7 tumor development." (PMID 31085177, 2019).